HDAC2 (histone deacetylase 2)
Diseases named in the same sentence as HDAC2 in open-access papers (continued):
Sharing a sentence is not in itself a finding about the gene and the disease.
peripheral T cell lymphoma (3 papers, 2022 to 2025). "Chidamid, an oral HDAC inhibitor of the benzamide class with specificity for HDAC1, HDAC2, HDAC3, and HDAC10 subtypes, has been approved for the treatment of relapsed or refractory peripheral T cell lymphoma." (PMID 41049003, 2025). "In peripheral T-cell lymphoma (PTCL), HDAC2 was detected to be overexpressed and considered to be a prognostic marker, particularly for patients with the PTCL-NOS subtype." (PMID 35887172, 2022). "Tucidinostat, a selective HDAC inhibitor having specificity for HDAC1, HDAC2, HDAC3, and HDAC10 subtypes, has been approved for the treatment of relapsed or refractory peripheral T cell lymphoma and is under clinical development globally for various other neoplastic and non-neoplastic diseases." (PMID 36352411, 2022).
pituitary adenomas (3 papers, 2022 to 2024). "Notably, histone deacetylase 2 expression is deficient in ACTH-pituitary adenomas in CD, contributing to glucocorticoid insensitivity, which is a hallmark of CD and a feature associated with nonremission." (PMID 38027207, 2023). "We also examined HDAC1, HDAC2, and HDAC3 expression by qRT-PCR in six GH-secreting, six ACTH-secreting, and six PRL-secreting human pituitary adenomas." (PMID 35646715, 2022). "We report that HDAC2 and 3, Class I HDAC members, are highly expressed in clinically non-functioning pituitary adenomas (NFPAs) compared to normal pituitary (NP) samples as determined by RT-PCR and immunohistochemical staining (IHC)." (PMID 35646715, 2022).
renal carcinoma (3 papers, 2022 to 2024). A carcinoma arising from the epithelium of the renal parenchyma or the renal pelvis. "Western blot, quantitative real time PCR (RT‒qPCR), RNA immunoprecipitation PCR (RIP-qPCR), methylated RIP-qPCR (MeRIP-qPCR) and RNA sequencing (RNA-seq) analyses were applied to study the YY1/HDAC2/YTHDC1/ANXA1 axis in renal cancer cells." (PMID 35974388, 2022). "In addition, we demonstrated that HDAC2 inhibitor treatment decreased the phosphorylation of ERK in renal cancer cells." (PMID 35974388, 2022). "Interestingly, we found that the HDAC2/YY1 complex suppressed YTHDC1 expression in renal cancer cells." (PMID 35974388, 2022). "In contrast, overexpression of HDAC2 decreased the expression of YTHDC1 in renal cancer cells." (PMID 35974388, 2022). "Furthermore, HDAC2 inhibitors could promote the antitumor effect of sunitinib partially through YTHDC1 in renal cancer cells." (PMID 35974388, 2022). "Histone deacetylases class 1 (HDAC1, HDAC2, HDAC3, and HDAC8) are expressed ubiquitously in almost all types of cancer except renal cancer." (PMID 37345150, 2023). "We also showed that coknockdown of HDAC2 and YY1 did not further increase the expression of YTHDC1 in renal cancer cells." (PMID 35974388, 2022).
sarcoma (3 papers, 2018 to 2024). A usually aggressive malignant neoplasm of the soft tissue or bone. "The previous results showed that the expression of class I HDACs, including HDAC1, HDAC2, and HDAC3, is associated with a poor prognosis of patients with sarcoma." (PMID 33637599, 2021). "We found that the mRNA expression of HDAC class I genes HDAC1, HDAC2 and HDAC3 was associated with prognosis in sarcoma." (PMID 33637599, 2021). "We analyzed the TCGA public database of 263 STS samples (cBioPortal.org) to identify the potential role of HDACs in sarcoma and observed an association between higher expression of class I HDACs, including HDAC1, HDAC2 and HDAC3 with shorter overall survival (p<0.001)." (PMID 33637599, 2021). "Since class I HDACs affect cell proliferation, we also detected the expression of HDAC1, HDAC2, and HDAC3 after treatment with chidamide and founded inhibited expression of HDAC1, HDAC2, and HDAC3 in the three sarcoma cell lines." (PMID 33637599, 2021).
tauopathy (3 papers, 2020 to 2025). Neurodegenerative disorders involving deposition of abnormal tau protein isoforms (tau proteins) in neurons and glial cells in the brain. "Furthermore, disruption of HNF-4A due to histone deacetylase 2 (HDAC2)-induced deacetylation upregulates AMPK, contributing to tauopathy." (PMID 41457120, 2025).
thyroid cancer (3 papers, 2019 to 2022). "Based on the evidence presented in this study, considerable epigenetic alternations, such as HDAC1 and HDAC2, in advanced thyroid cancer were investigated and more epigenetic alterations are being studied." (PMID 30669676, 2019). "By knocking out HDAC1 and HDAC2 using clustered regularly interspaced short palindromic repeats (CRISPR/Cas9), we investigated the impact of HDAC loss and how acetylation is regulated in thyroid cancer cells and observed the downstream signaling pathways and cell cycle regulation." (PMID 30669676, 2019).
urothelial bladder carcinoma (3 papers, 2011 to 2024). "Both HDAC1 and HDAC2 were significantly associated with higher tumor grades of urothelial bladder carcinoma." (PMID 39063083, 2024). "HDAC-2 overexpression has been correlated with HG lip SCC, NSCLC, esophageal, gastric, hepatocellular, prostate, serous subtype of endometrial and ovarian and urothelial bladder carcinoma, the latest more often accompanied by adjacent carcinoma in situ when HDAC-2 was overexpressed." (PMID 33799478, 2021). "Given the similarity between the HDAC2 and HDAC4 proteins in both their functions, these results suggest that only certain HDACs are involved in the XPC gene silencing in the urinary bladder transitional cell carcinomas." (PMID 21507255, 2011).
Airway obstruction (2 papers, 2016 to 2023). Obstruction of conducting airways of the lung. "At present, the relationship between HDAC2 and the severity of airway obstruction in COPD patients is unclear." (PMID 26809128, 2016). "Given that HDAC activity may reflect the severity of airway obstruction, the correlation of HDAC2 expression with the severity of airway obstruction in COPD patients was analyzed." (PMID 26809128, 2016).
alcohol dependence (2 papers, 2016 to 2019). Physical and psychological dependence on alcohol. "Collectively, these observations raised the possibility that adaptive epigenetic changes involving HDACs, and in particular HDAC2, in the AMG may be important regulatory mechanisms that underlie expression of genes implicated in the development and pathogenesis of alcohol dependence." (PMID 27766083, 2016).
allergies (2 papers, 2019 to 2022). "Taken together, these reports implicate the roles of HDACs including HDAC2 in allergies and anaphylaxis." (PMID 31597362, 2019). "Given the fact that TGFβ1 confers oral tolerance to food allergens, HDAC2 might act as a negative regulator of allergies and anaphylaxis." (PMID 31597362, 2019).
behavioral disorders (2 papers, 2020 to 2025). "In conclusion, SIS is associated with behavioral disorders in first and second-generation mice these behaviors are associated with increased HDAC2 and GCN5, as well as decreased diameter and number of neurons in the hippocampus." (PMID 40051733, 2025). "The neurosynaptic injury resulting from the lncRNA11496/Mef2c/HDAC2 pathway could serve as a new mechanism of mental and behavioral disorders induced by T. gondii." (PMID 32499679, 2020). "NAC reduces behavioral disorders after SIS (first and second generation) by reducing the expression of GCN5 and HDAC2 and increasing neuronal diameter in the hippocampus." (PMID 40051733, 2025). "The aim of this study is to the effect of NAC through the modulation of HDAC2 and GCN5 in the hippocampus and investigate behavioral disorders in the first and second generation of SIS mice." (PMID 40051733, 2025). "The aim of the researchers of this project is to investigate the effect of NAC on behavioral disorders in the first and second generations of mice subjected to SIS focusing on GCN5 and HDAC2 gene expression as well as CA1 and CA3 histological changes in the hippocampus." (PMID 40051733, 2025).
chronic kidney disease (2 papers, 2021 to 2023). Impairment of the renal function secondary to chronic kidney damage persisting for three or more months. "We observed that HDAC1 and HDAC2 were upregulated in chronic kidney disease (CKD) kidney tissue." (PMID 37153759, 2023).
chronic lymphocytic leukemia (2 papers, 2019 to 2023). "The inhibition of HDAC1 and HDAC2 but not HDAC3, HDAC6, or HDAC8 enhanced the sensitivity of chronic lymphocytic leukemia (CLL) cells to TRAIL-induced apoptosis." (PMID 36968022, 2023).
clear cell renal cell carcinoma (2 papers, 2023). "In clear cell renal cell carcinoma, the YY1/HDAC2 complex reduces the expression of YTHDC1, which modulates the sensitivity of ccRCC to sunitinib by targeting the ANXA1-MAPK pathway." (PMID 37495623, 2023). "HDAC2 downregulated expression of the m6A reader, YTHDF2, by modulating clear cell renal cell carcinoma sensitivity to sunitinib therapy." (PMID 37691948, 2023).
Cornelia de Lange syndrome (2 papers, 2021). A rare syndrome characterized by low birth weight, delayed growth, intellectual disabillity, behavioral problems, and a distinctive facial appearance (thin, arched eyebrows, low set ears, small teeth, and small nose). "Amongst these OTUD5 substrates are ARID1A/B, HDAC2, and HCF1, mutations of which underlie different developmental disorders (Coffin–Siris and Cornelia de Lange syndromes, X-linked mental retardation 3) that exhibit considerable phenotypic overlap with LINKED patients." (PMID 33335288, 2021).
diabetic foot ulcer (2 papers, 2021 to 2023). "In chronic diabetic foot ulcer (DFU) an increase of HDAC2 expression also happens where dysfunctional endothelial progenitor cells (EPCs) plays a major role in inhibiting vascular complication in DFU patient." (PMID 36909892, 2023). "Overexpression of HDAC2 has been observed in patients with diabetic foot ulcers, which mainly contributes to endothelial progenitor cell dysfunction and the production of ROS and pro-inflammatory factors in endothelial progenitor cells in hyperglycemic conditions." (PMID 34071497, 2021). "HDAC2 inhibition can also upregulate SIRT1 expression and ensure SIRT1-mediated protection against diabetic foot ulcers." (PMID 34071497, 2021).
ependymoma (2 papers, 2020 to 2023). A WHO grade II, slow growing tumor of children and young adults, usually located intraventricularly. "LSD1, HDAC1 and HDAC2 are all highly expressed across ependymoma groups, but HDAC1/2 transcription is even more pronounced in ZFTA ependymoma." (PMID 37085539, 2023).
esophageal cancer (2 papers, 2023 to 2024). A primary or metastatic malignant neoplasm involving the esophagus. "It should be noted that HDAC inhibitors have illustrated anticancer properties, with high HDAC2 expression correlating with increased aggression in esophageal cancer." (PMID 38562378, 2024). "The expression levels of HDAC1, HDAC2 and HDAC3 were significantly up-regulated in esophageal cancer specimens compared to normal specimens." (PMID 37171386, 2023). "Our study showed that both tumor-specific histone methylation and higher expression levels of histone deacetylases HDAC1, HDAC2 and HDAC3 are involved in miR-497 downregulation in esophageal cancer cells, suggesting the epigenetic complexity of miRNA deregulation." (PMID 37171386, 2023).
fibrosis (2 papers, 2020 to 2022). the formation of excess fibrous connective tissue in an organ or tissue in a reparative or reactive process. "Interestingly, these downregulated miRNAs are also known to increase the expression of target genes HDAC1, HDAC2, and RB1 which increase global chromatin accessibility, increase cardiac fibrosis and decrease cardiac function." (PMID 33175850, 2020).
HCMV infection (2 papers, 2013 to 2015). "PML was required for accumulation of activated STAT1 and STAT2, interacted with them and HDAC1 and HDAC2, and was associated with ISG promoters after HCMV infection." (PMID 25812002, 2015). "Since PML directly interacts with HDAC1 and HDAC2, which may affect ISG transcription, we also assessed whether PML associates with these HDACs after UV-HCMV infection." (PMID 25812002, 2015). "Furthermore, after UV-HCMV infection, PML formed a protein complex with STAT1, STAT2, HDAC1, and HDAC2 and associated with ISG promoters." (PMID 25812002, 2015).
head and neck cancer (2 papers, 2015 to 2019). A primary or metastatic malignant neoplasm affecting the head and neck. "We next examined HDAC1, HDAC2 and HDAC6 levels in 8 head and neck cancer cell lines and normal human oral keratinocytes (HOK)." (PMID 26000099, 2015). "We measured HDAC1, HDAC2 and HDAC6 levels in 20 frozen tissue samples from head and neck cancer patients (10 tumor and 10 adjacent normal controls) by real-time PCR." (PMID 26000099, 2015).
HIV-1 infection (2 papers, 2014 to 2015). The type species of lentivirus and the etiologic agent of acquired immunodeficiency syndrome (AIDS). "Taken together these findings suggest that HDAC3 is an essential target to disrupt HIV-1 latency, and inhibition of HDAC2 may also contribute to the effort to purge and eradicate latent HIV-1 infection." (PMID 25136952, 2014). "On the other hand, we found that important genes for transcriptional silencing as methyltransferases and histone deacetylases (i.e. HDAC2) were down-regulated in non-activated cells but, up-regulated in activated cells after HIV-1 infection." (PMID 25875202, 2015).
Hyperglycemia (2 papers, 2021 to 2023). An increased concentration of glucose in the blood. "HDAC2 has been reported to respond to hyperglycemia or diabetes-induced oxidative stress and has been implicated in high glucose-induced damage in endothelial progenitor cells." (PMID 36900446, 2023). "In addition, hyperglycemia suppressed expressions of heme oxygenase 1 (HO-1) and SIRT1, which are restored by treatment with HDAC2 siRNA." (PMID 36900446, 2023).
idiopathic pulmonary arterial hypertension (2 papers, 2020 to 2022). A sporadic form of pulmonary arterial hypertension (PAH) characterized by elevated pulmonary arterial resistance leading to right heart failure. "One study reported that the expression levels of HDAC1, HDAC2, and HDAC8 were upregulated in patients with idiopathic pulmonary arterial hypertension." (PMID 35126818, 2022). "Comprehensive analysis of expression and regulation of class I HDACs (HDAC1, HDAC2, HDAC3 and HDAC8) was performed in cardiopulmonary tissues and adventitial fibroblasts isolated from pulmonary arteries (PAAF) of idiopathic pulmonary arterial hypertension (IPAH) patients and healthy donors." (PMID 32733053, 2020).
keloid (2 papers, 2019 to 2022). An irregularly shaped, elevated mark on the skin caused by deposits of excessive amounts of collagen during wound healing. "applied CUDC-907, a dual inhibitor of PI3K/Akt/mTOR pathway and histone deacetylases 2 (HDAC2) to human keloid fibroblasts (KFs), resulting in suppressed KF proliferation, migration, collagen production as well as reduced TGF-β1 in vitro." (PMID 36325354, 2022). "Other studies found evidence for histone modification such as upregulated HDAC2 in keloid tissue and expression of non-coding RNAs in keloids." (PMID 31440236, 2019).
liver failure (2 papers, 2019 to 2021). A liver disease characterized by the liver losing or has lost all of its function. "The serum level of HDAC2, IL-18, and IL-1β in liver failure patients was higher than healthy donors." (PMID 33431796, 2021). "From the clinical study, the high serum levels of HDAC2, IL-18, IL-1β were found in liver failure patients, when compared with normal subjects." (PMID 33431796, 2021). "A clinical study has shown that the activities of HDAC1 and HDAC2 are obviously elevated in the patients with chronic hepatitis B, especially in the patients with liver failure." (PMID 31183000, 2019).
lupus (2 papers, 2016 to 2023). "In addition, we found that the expression of HDAC1 and HDAC2 in the lupus tubulointerstitium tissue was significantly negatively correlated with the GFR of patients (R2 = 0.8172, p = 0.0052, and R2 = 0.8651, p = 0.0024 respectively)." (PMID 37153759, 2023).
mesenchymal tumors (2 papers, 2021). "Similar findings regarding HDAC-1 have been reported in skin melanoma and in mesenchymal tumors, suggesting that HDAC-2 is the class I isoform more likely associated with the pathogenesis of UMs." (PMID 34638249, 2021). "According to their study, HDAC-2 was the most frequently expressed isoform in translocation-associated sarcomas in comparison to the other mesenchymal tumors." (PMID 34441281, 2021). "Finally, Pacheco and O Nielsen tried to elucidate the role of HDAC-1 and HDAC-2 in a large series of mesenchymal tumors, comprised of 1332 cases, representing 44 categories of both malignant and borderline tumors." (PMID 34441281, 2021).
metastasis (2 papers, 2011 to 2021). The spread or migration of cancer cells from one part of the body (where they first appeared) to another. "Clinicopathologic data showed that increased HDAC2 expression is correlated with liver metastasis and higher T stages." (PMID 33325150, 2021).
multiple sclerosis (2 papers, 2018 to 2022). A progressive autoimmune disorder affecting the central nervous system resulting in demyelination. "To expand our understanding of the role of HDAC2-mediated regulation of IL-17-driven inflammation in vivo, we extended our studies to include experimental autoimmune encephalomyelitis (EAE), a mouse model of human multiple sclerosis." (PMID 30375383, 2018).
myeloid leukemia (2 papers, 2014 to 2024). A clonal proliferation of myeloid cells and their precursors in the bone marrow, peripheral blood, and spleen. "MiDAC has been shown to contain protein subunits MIDEAS, HDAC1, HDAC2 and DNTTIP1 in myeloid leukemia K562 cells and human T lymphocyte CEM cells." (PMID 38781120, 2024).
Myocardial fibrosis (2 papers, 2023 to 2025). "In addition, transcription factors such as Tead1 and Hdac2 can be verified by further experiments in the future to find their potential association with adverse outcomes such as myocardial fibrosis." (PMID 40595870, 2025). "Tead1 and Hdac2 may be potential targets for inhibiting myocardial fibrosis and preventing adverse outcomes of MI after further experimental verification." (PMID 40595870, 2025).
oligodendroglioma (2 papers, 2021 to 2022). A well-differentiated (WHO grade II), diffusely infiltrating neuroglial tumor, typically located in the cerebral hemispheres. "As oligodendroglioma (n = 3) was compared with normal (n = 7) in Shai’s 2003 study, HDAC2 was upregulated and showed a fold change of 3.24 (p = 6.99E-04)." (PMID 34540896, 2021).
pituitary tumor (2 papers, 2019 to 2022). A benign or malignant neoplasm affecting the pituitary gland. "Because the increase of HDAC2 and HDAC3 levels in pituitary tumors were similar, and there is no HDAC2-specific inhibitor available, we decided to focus our subsequent studies on HDAC3." (PMID 35646715, 2022).
pneumonia (2 papers, 2023 to 2026). An acute, acute and chronic, or chronic inflammation focally or diffusely affecting the lung parenchyma, caused by an infection in one or both of the lungs (by bacteria, viruses, fungi, or mycoplasma.). "Pathway readouts supported actions on complementary axes (TLR4-IRAK1, STING1-IFN-β, FPR1-AKT, CASP8, and HDAC2-H3K9ac), providing a mechanistic basis for their collective protection against pneumonia." (PMID 41484909, 2026).
progeria (2 papers, 2018 to 2019). "As a whole, these results indicate TSA as a good pharmacological tool for progeria cells as rescue of HDAC2-lamin A/C interaction occurs in TSA-treated HGPS cells, while excess histone acetylation is avoided." (PMID 30766871, 2019).
rectal cancer (2 papers, 2023 to 2024). A primary or metastatic malignant neoplasm that affects the rectum. "Moreover, we included patients with rectal cancer who received neoadjuvant therapy and stratified them according to pretreatment HDAC2 expression levels to assess treatment response." (PMID 38804602, 2024). "Low HDAC2 expression promotes EMT and rectal cancer metastasis by upregulating H19/MMP14." (PMID 37631010, 2023).